C22orf39 (chromosome 22 open reading frame 39)
Description:
Negatively regulates long-term potentiation and modulates adult synaptic plasticity. Stabilizes the interaction of RTN4 isoform A/Nogo-A with its receptors, inhibiting clustering of postsynaptic AMPA receptors at synaptic sites. Upon neuronal stimulation, degraded at synapses, reducing RTN4 signaling and allowing AMPA receptor clustering at individual synapses.
Synonyms: MGC74441; Pants
Tractability: Antibody: its Gene Ontology location is reachable by antibodies, with medium confidence.
Gene: Protein-coding gene on chromosome 22 (19,351,368 to 19,447,711, reverse strand). Ensembl gene ENSG00000242259.
Subcellular location: Synapse; Synaptic cleft
Subcellular location (Human Protein Atlas): Endoplasmic reticulum
Gene Ontology:
Molecular function: protein binding
Biological process: negative regulation of long-term synaptic potentiation; regulation of synaptic plasticity
Cellular component: mitochondrion; synapse; synaptic cleft
Genetic constraint (gnomAD): Loss-of-function variants: 20 observed, 11.33 expected, observed/expected ratio (o/e) 1.76, 90% interval 1.18 to 1.96. The synonymous counts are far from expectation, so gnomAD's model fits this gene poorly and the ratio says little. Missense variants: 195 observed, 117.56 expected, observed/expected ratio (o/e) 1.66, 90% interval 1.48 to 1.86. Synonymous variants: 63 observed, 45.88 expected, observed/expected ratio (o/e) 1.37, 90% interval 1.12 to 1.69.
Homologues: Orthologues: chimpanzee C22H22orf39 (97% identical), rabbit C22orf39 (90% identical), dog C22orf39 (84% identical), guinea pig C22orf39 (83% identical), pig C22orf39 (83% identical), mouse 2510002D24Rik (70% identical), Drosophila melanogaster CG15908 (26% identical), zebrafish si:ch211-51h9.6 (23% identical), tropical clawed frog c1h22orf39 (22% identical).
Diseases named in the same sentence as C22orf39 in open-access papers:
C22orf39 is named in the same sentence as 1 disease in open-access papers, as found by Europe PMC text mining. Sharing a sentence is not in itself a finding about the gene and the disease. The quoted sentences say what the papers report.
Obesity (1 paper, 2020). Accumulation of substantial excess body fat. "From the GWAS, the significant markers associated with obesity-related traits including body weight (CACNA1B, C22orf39, U6, MYH14, PTPN2, SEH1L) and blood sugar (PRSS55, GRIK2), were identified." (PMID 33182249, 2020).